ATM (ATM serine/threonine kinase)
Diseases named in the same sentence as ATM in open-access papers (continued):
Sharing a sentence is not in itself a finding about the gene and the disease.
cancer (continued). "The variation of ATM gene can affect the normal function of the protein and increase the risk of cancer." (PMID 30709340, 2019). "Meanwhile, ATM was identified as the responsible gene of ataxia telangiectasia, a hereditary disease characterized by cancer predisposition." (PMID 31805725, 2019). "Accumulating evidence demonstrates that ATR-checkpoint kinase 1 (Chk1) pathway can be considered as potential therapeutic strategies for ATM-deficient cancers." (PMID 30975222, 2019). "For the NPAT/ATM locus it is tricky to be sure of the causal variant and gene, and work is ongoing in mouse models to investigate the mechanism, but it is tempting to conclude that the cancer gene, ATM, is causal." (PMID 31012484, 2019). "Instead, most were in moderate-penetrance genes that confer a two- to four-fold increase in cancer risk (eg, ATM and CHEK2) as well as low-penetrance mutations (eg, monoallelic MUTYH and APC I1307K)." (PMID 34322651, 2019). "We explored the underlying relationship between rs189037 SNP of ATM gene and the occurrence of cancer using a meta-analysis that included 15 case-control studies (8660 cases and 9259 controls)." (PMID 30709340, 2019). "Overall, ATM rs189037 A allele exhibited a 1.17-fold increased risk of cancer compared with the G allele (OR = 1.17, 95% CI = 1.0–1.30)." (PMID 31201228, 2019). "A single 15Gy RT dose suppressed tumor growth in a preclinical model when ATM was deleted in cancer cells vs. when deleted in endothelial cells, underlining the interest in testing ATM inhibitors in combination with highly conformal RT." (PMID 31649878, 2019). "Epidemiological studies have indicated associations between ATM rs1801516 polymorphism and different types of cancer, but their results are inconsistent." (PMID 30384829, 2018). "In response to DNA damage, cancer cells tend to stop proliferation through the activation of the checkpoint kinases 1 and 2 (ChK1/2) and ataxia telangiectasia mutated (ATM) to allow DNA repair." (PMID 29671772, 2018). "Overall, a candidate disease-causing mutation in a cancer predisposing gene was identified in 18 patients (14.9%), with ATM and CHEK2 representing 61.1% of the cases." (PMID 29659569, 2018). "Mutations in the ATM gene are associated with an increased risk for many of the same cancers associated with BRCA mutations, such as breast, pancreatic, and prostate." (PMID 29659587, 2018). "Several ATM polymorphism loci have been studied in different types of cancer, including rs1801516, which is a common nonsynonymous variant on this gene." (PMID 30384829, 2018). "Ataxia telangiectasia-mutated (ATM) gene is one of the most frequently studied genes in cancer occurrence and progression." (PMID 30384829, 2018). "Meta-analyses have also been performed to assess ATM rs1801516 polymorphism and cancer predisposition, but the results are inconsistent." (PMID 30384829, 2018). "To further evaluate the effect of ATM rs1801516 polymorphism on cancer risk, we conducted this meta-analysis." (PMID 30384829, 2018). "Many studies have reported that genetic variants in ATR/CHEK1 and ATM/CHEK2 are associated with cancer risk." (PMID 29928473, 2018). "Overall, our data strongly support the role of these ATM mutations in cancer development, in these families." (PMID 29271107, 2018). "The BRAT1 protein participates in DNA damage responses, cell growth, and apoptosis by interacting with the tumor-suppressor protein BRCA1 (breast cancer 1) and the ATM protein (ataxia telangiectasia mutated) in humans." (PMID 30093865, 2018).
cancer (continued). "Here, the authors show that while this is true for tumours with recurrent mutations, cancers with recurrent CNAs show neoantigen-independent infiltration driven by cytokine production downstream of the DNA damage sensor ATM." (PMID 29615613, 2018). "We show mathematically that the oscillatory phase space can be recovered and so apoptosis can be initiated in the types of cancer cells caused by Wip1 overexpression or ATM deficiency as with suppression of Wip1 overexpression and degradation of Wip1." (PMID 29337287, 2018). "Loss of ATM and c-myc amplification/overexpression are often mutually exclusive in multiple cancer types, suggesting a redundancy in the pathway." (PMID 29238697, 2017). "Although the germline ataxia-telangiectasia syndrome is due to compound heterozygosity, haplo-insufficiency in ATM is known to increase radio-sensitivity as well as increase risk of cancer development." (PMID 28055970, 2017). "Targeted sequencing using a next generation sequencing panel of cancer genes demonstrated that patient A had a frameshift mutation in the ATM gene at position 1455, along with 29 other somatic mutations." (PMID 28055970, 2017). "Ataxia-Telangiectasia Mutated (ATM) is a multifunctional kinase that plays complex and controversial roles in cancer." (PMID 28423511, 2017). "More well-designed studies that include larger sample sizes should be performed in the future to further evaluate the association between the ATM gene and cancers." (PMID 29246212, 2017). "In cancers that lack homologous repair capacity due to BRCA1/2 or ATM dysfunction or loss, PARP inhibitors can lead to cancer cell death via mechanisms of synthetic lethality." (PMID 28993799, 2017). "Although ATM has often been linked to cancer development, ATM signaling can also be advantageous to cancer cells, particularly in resistance to radiation and chemotherapy." (PMID 29348882, 2017). "Of 24 cancer types with NHEJ mutations, 15 (62.5%) cancer types revealed ATM to be the most commonly mutated gene." (PMID 28055970, 2017). "Analysis of 22 DNA repair genes in The Cancer Genome Atlas (TCGA) data revealed mutations in 15.9% of 9064 tumors across 24 cancer types, with ATM mutations being the most prevalent." (PMID 28055970, 2017). "This disease, caused by a loss of ATM function, is characterised by progressive cerebellar degeneration, telangiectasia, immunodeficiency, growth retardation, genomic instability, cancer susceptibility and profound sensitivity to IR." (PMID 27602502, 2016). "ATM (ataxia-telangiectasia, mutated) is an important cancer susceptibility gene that encodes a key apical kinase in the DNA damage response pathway." (PMID 27658045, 2016). "The rarity of mutations in PALB2, CHEK2 and ATM make it difficult to estimate precisely associated cancer risks." (PMID 27595995, 2016). "Here we report that 72% of cancer-associated ATM mutations are missense mutations that are enriched around the kinase domain." (PMID 27304073, 2016). "Here we report that cancer-associated ATM missense mutations are highly enriched in the kinase domain." (PMID 27304073, 2016). "Odds ratios (ORs) were calculated to estimate the association between ATM genetic polymorphisms and cancer risk." (PMID 27764772, 2016). "Here we have identified an alternative splicing-coupled NMD switch exon critical for ATM expression and examined its importance in cancer risk." (PMID 26732650, 2016). "ATM is an important cancer susceptibility gene that encodes a critical apical kinase of the DNA damage response (DDR) pathway." (PMID 26732650, 2016).
cancer (continued). "Amongst the cancer-associated ATM mutations are truncating, frame-shift or splice site mutations, which are likely to affect ATM function and/or protein expression." (PMID 27602502, 2016). "Here we report that 72% of human cancer-associated ATM mutations are missense mutations that are highly enriched in the kinase domain." (PMID 27304073, 2016). "While previous studies have mostly focused on the complete loss of ATM (Atm-/-, truncating mutations), recent sequencing analyses identified a large number of missense ATM mutations in human cancers with limited information on their biological function." (PMID 27304073, 2016). "Disrupting ATM, either through mutation, RNA interference or small-molecule inhibition, increase the sensitivity of cancer cells to PARP inhibitors." (PMID 27613518, 2016). "By direct ATM sequencing of 3 of these carriers, we identified the cancer-prone intronic c.8786 + 8A > C variant in one patient and the c.2572 T > C (p.F858L) missense mutation in other two patients." (PMID 27599564, 2016). "Using murine models, we showed that expression of ATM-KD causes cancer more frequently and rapidly than loss of ATM, and the AtmKD/- cancers are selectively hypersensitive to Topo1 inhibitors." (PMID 27304073, 2016). "Low levels of ATM are associated with higher sensitivity to PARP inhibitors in several cancer cell lines." (PMID 27613518, 2016). "Our meta-analysis of 2000 patients from 9 studies provided evidence of an association between the ATM polymorphism rs1801516 and the risk of developing late fibrosis in cancer patients after radiotherapy." (PMID 27057881, 2016). "A number of studies have investigated the joint effect between the ATM gene and radiation exposure on cancer risk." (PMID 27764772, 2016). "Along with A-T associated mutations, several ATM screenings in cancer patients identified missense ATM variants, particularly amino acid substitutions that are not expected to be associated with A-T." (PMID 27599564, 2016). "In the past two decades, about 100 studies have been published to evaluate the associations of ATM genetic polymorphisms with cancer risk." (PMID 27764772, 2016). "The mutation density calculated using the Gaussian Kernel model revealed that cancer associated missense ATM mutations in TCGA cluster around the C-terminal kinase domain, while truncating mutations (in A-T or TCGA) span the entire ATM protein." (PMID 27304073, 2016). "Somatically occurring ATM mutations are also prevalent in a number of sporadic human cancers, most notably leukemias and carcinomas of the breast and lung." (PMID 25625042, 2015). "Significant increase of cancer risk was connected with the p.Asp1853Asn polymorphism in the ATM gene and minor homozygotes were at higher cancer risk (OR 4.52; 95% CI 1.16-17.56; p = 0.029)." (PMID 25591549, 2015). "ATM deficiency is also associated with radiosensitivity and increased incidence of cancer, which are attributed to its role in responding to DNA damage." (PMID 25967673, 2015). "The authors point out that ATM and Mre11 complex mutations occur in various cancer types, providing the opportunity to manipulate this sensitizing interaction in various contexts for clinical benefit." (PMID 26404381, 2015). "In this review, we will focus on cancer-associated defects in ATM-mediated DNA double-strand (DSB) repair and their potential targeting." (PMID 26113859, 2015). "Some specific ATM alleles were correlated with the increased risk of various cancers, including lung, breast, and prostate cancer." (PMID 25861265, 2015). "To provide evidence that such an approach is feasible, we have recently shown that XRCC1-deficient cancer cells are sensitive to ATM, DNA-PKcs, and ATR inhibitors." (PMID 25111287, 2014). "In the human autosomal recessive disorder ataxia telangiectasia, ATM gene is mutated, resulting in genome instability, immunodeficiency, hypersensitive to IR, and cancer predisposition." (PMID 25386189, 2014).
cancer (continued). "Several reports suggest that germline ATM mutations enhance cancer predisposition not only when both alleles are affected but also when a single copy is hit." (PMID 24681585, 2014). "The large body of literature produced over the years has reported that ATM variants can have different and frequently opposing effects in cancer predisposition, which causes a multitude of phenotypes." (PMID 25247188, 2014). "This condition can explain why, in many cases, AT heterozygous with ATM in missense mutations is associated with a high risk of cancer incidence with respect to heterozygous with a truncated version of ATM." (PMID 25247188, 2014). "By now, many ATM mutations have been reported to increase cancer predisposition, including truncation and missense mutations." (PMID 25247188, 2014). "About 20% of patients with CLL show ATM deletion, an anomaly also seen in almost all cancer, and is usually associated with an adverse outcome." (PMID 23369149, 2013). "Predicted mRNA targets of the miRNAs significantly regulated after ATM depletion included many genes associated with cancer formation and progression, such as SOCS1 and the proto-oncogene MAF." (PMID 23741392, 2013). "These individuals with an ATM mutation in one allele are spared from most of the symptoms of A-T, but are more susceptible to cancer and ischemic heart disease." (PMID 24358288, 2013). "This study provided new information on the ethnic distribution of ATM variants in a regional US population, and is the first to determine the prevalence of ATM variants in AI cancer patients." (PMID 24416720, 2013). "When we further investigated these miRNA and possible targets we highlighted additional evidence of a cancer-susceptibility profile in ATM-deficient human mammary epithelial cells." (PMID 23741392, 2013). "A total of nine studies including 4,470 cases and 4,862 controls were analyzed for ATM IVS 22-77 T>C association with cancer risk in this meta-analysis." (PMID 22276117, 2012). "In conclusion, well-designed, unbiased studies should be done to gain a more comprehensive understanding of the association between the ATM gene and cancer risk." (PMID 22276117, 2012). "RASSF1A has been shown by several groups to be phosphorylated by ATM and the ATM site polymorphisms are present in several cancer types." (PMID 22701175, 2012). "We found a paradoxical role for the ATM rs664677 polymorphism contributing to both cancer suppressing and promoting effects." (PMID 22276117, 2012). "Results of the pooled data analyses for the 9 studied and subgroup analysis for ATM rs664677 and cancer risk." (PMID 22276117, 2012). "Overall, nine studies, involving 4,470 cases and 4,862 controls, concerning ATM rs664677 polymorphism and cancer susceptibility were available for this meta-analysis." (PMID 22276117, 2012). "In recent years, there has been considerable interest in understanding the possible role of ATM gene in assessing the risk associated with cancer." (PMID 22529920, 2012). "For example, mutations affecting ataxia telangiectasia mutated (ATM), a protein which senses DNA damage and initiates a repair cascade, can lead to increased radiosensitivity and cancer susceptibility." (PMID 23249860, 2012).
cancer (continued). "The Ataxia-telangiectasia-mutated (ATM) gene in humans was identified as the basis of a rare autosomal disorder leading to cancer susceptibility and is now well known as an important signal transducer in response to DNA damage." (PMID 22350747, 2012). "Recent data indicate that several polymorphisms of key regulators from the DNA damage repair pathway (i.e. 53BP1 and ATM) are associated with cancer development susceptibility." (PMID 22200742, 2012). "Some cancer-prone human syndromes arise from defects in specific DNA damage response and DNA repair genes, such as ataxia telangiectasia mutated (ATM), nibrin (also known as NBS1), BRCA1 and BRCA2." (PMID 24213112, 2011). "Using cultured tumor cells, we recently confirmed that metformin promotes activation of ATM and ATM targets, such as the protein kinase Chk2, suggesting a causal linkage between metformin's mechanism of action and metformin's cancer preventative effects." (PMID 22203527, 2011). "For instance, people or animals with defects in the ATM/Chk2 pathway display heightened predisposition to cancer, although cells deficient in ATM or Chk2 are otherwise viable." (PMID 21851590, 2011). "The presence of specific variants in the ATM gene further increased the risk of CBC specifically in those women who received RT for their first cancer." (PMID 22087758, 2011). "The clinical symptoms associated with loss of ATM activity are neurodegeneration, extreme cellular sensitivity to radiation, immunodeficiency, and a predisposition to cancer." (PMID 21980462, 2011). "Although a large number of genes have been implicated in the genesis of cancer and neurodegeneration, only two, parkin and ATM, have been shown to strongly overlap." (PMID 21203498, 2010). "Analysis of coding exons of 518 protein kinases in 210 different human cancers, indicated that ATM gene ranked third in terms of mutation frequency, behind Titin and BRAF (B-Raf proto-oncogene serine/threonine-protein kinase)." (PMID 21054854, 2010). "53BP1-deficient mice are growth retarded, radiosensitive, immunodeficient and predisposed to cancer, a phenotype that resembles ATM or H2AX knockout mice." (PMID 19008195, 2009). "In particular, genetic deficiency of ATM in humans is responsible for the ataxia-telangiectasia syndrome characterized by a high susceptibility to both DNA damage and cancer." (PMID 19421407, 2009). "The hypersensitivity of FA deficient cells to CHK1 and ATM inhibition suggests a framework for cancer therapy by manipulation of DNA repair." (PMID 19371427, 2009). "Generally, the idea is that there are two groups of ATM heterozygotes in the general population, each with different cancer risks: those with a wild-type and a truncating mutation allele and those with a wild-type and a missense mutation allele." (PMID 17428320, 2007). "Loss of ATM function is also associated with increased genomic instability that contributes to the increased incidence of cancers seen in this syndrome." (PMID 14970866, 2004). "The 3161G>C variant is located in the β-adaptin domain of the ATM protein and has been suggested to be linked to an increased cancer risk." (PMID 15280931, 2004). "Screening for heterozygous mutations in the gene homozygously mutated in the cancer-prone, radiosensitivity disorder, ataxia-telangiectasia (ATM: AT mutated) in radiosensitive patients has been vigorously pursued during the past few years." (PMID 12698192, 2003).